ENSG00000252774
Synonyms: LOC124900364
Gene: Small nucleolar RNA gene on chromosome 15 (64,342,539 to 64,342,698, forward strand). Ensembl gene ENSG00000252774.
Gene Ontology:
Biological process: RNA processing
Cellular component: nucleolus
Homologues: Paralogues in human: SNORA48 (65% identical), SNORA48B (64% identical).